XAGE1A (X antigen family member 1A)
Synonyms: XAGE-1; CT12.1; GAGED2; XAGE1; CT12.1a; CT12.1B; CTP9; XAGE1B
Tractability: PROTAC: UniProt records ubiquitination sites on it; ubiquitination databases record sites on it.
Gene: Protein-coding gene on chromosome X (52,495,808 to 52,500,812, forward strand). Ensembl gene ENSG00000204379.
Subcellular location (Human Protein Atlas): Nucleoplasm
Gene Ontology:
Molecular function: protein binding
Homologues: Paralogues in human: XAGE1B (100% identical), XAGE2 (31% identical), XAGE5 (28% identical), PAGE3 (27% identical), XAGE3 (27% identical), PAGE4 (26% identical), GAGE1 (19% identical), GAGE12C (19% identical), GAGE12D (19% identical), GAGE12E (19% identical), GAGE12F (19% identical), GAGE12G (19% identical), and 10 more.
Diseases named in the same sentence as XAGE1A in open-access papers:
XAGE1A is named in the same sentence as 4 diseases in open-access papers, as found by Europe PMC text mining. Sharing a sentence is not in itself a finding about the gene and the disease. The quoted sentences say what the papers report.
lung carcinoma (3 papers, 2021 to 2025). "Due to the upregulation of the candidate biomarker XAGE1A in lung cancer tissues, which is inconsistent with its downregulated expression in plasma, we initially chose another candidate biomarker SLC16A4 for further analysis." (PMID 40867526, 2025). "The levels of XAGE-1a and XAGE-1d in lung cancer patients are 1620 ng/L and 2510 ng/L, respectively, which are much higher than those of the widely used cancer marker CEA, suggesting that they are excellent biomarkers for the diagnosis of lung cancer." (PMID 35574342, 2022).
COVID-19 (1 paper, 2022). A disease caused by infection with severe acute respiratory syndrome coronavirus 2. "We speculate that the high expression of these immune-related genes can alleviate the aggravation of COVID-19 symptom severity, such as GAGE12F, TNMD, MAGEA6, MAGED2, and XAGE1A." (PMID 36118230, 2022).
tumor (3 papers, 2008 to 2021). "Six loci (CLEC3B (previously TNA), MGP, RASSF1, SDK2, SERPINB5 and XAGE1A (previously GAGED2)) with statistically significantly higher methylation in tumor samples compared with non-tumor samples were identified." (PMID 18947422, 2008).
XAGE1A also shares sentences with these, for which no sentence is quoted: cancer (2 papers).